CHAC1 (ChaC glutathione specific gamma-glutamylcyclotransferase 1)
Description:
Catalyzes the cleavage of glutathione into 5-oxo-L-proline and a Cys-Gly dipeptide. Acts specifically on glutathione, but not on other gamma-glutamyl peptides. Glutathione depletion is an important factor for apoptosis initiation and execution. Acts as a pro-apoptotic component of the unfolded protein response pathway by mediating the pro-apoptotic effects of the ATF4-ATF3-DDIT3/CHOP cascade. Negative regulator of Notch signaling pathway involved in embryonic neurogenesis: acts by inhibiting Notch cleavage by furin, maintaining Notch in an immature inactive form, thereby promoting neurogenesis in embryos.
Synonyms: MGC4504
Tractability: PROTAC: ubiquitination databases record sites on it.
Gene: Protein-coding gene on chromosome 15 (40,952,962 to 40,956,512, forward strand). Ensembl gene ENSG00000128965.
Subcellular location: Cytoplasm, cytosol; Golgi apparatus, trans-Golgi network
Subcellular location (Human Protein Atlas): Mitochondria
Pathways (Reactome):
Cellular responses to stimuli: Response of EIF2AK1 (HRI) to heme deficiency
Metabolism: Glutathione synthesis and recycling
Gene Ontology:
Molecular function: glutathione specific gamma-glutamylcyclotransferase activity; protein binding; Notch binding
Biological process: intrinsic apoptotic signaling pathway in response to endoplasmic reticulum stress; negative regulation of Notch signaling pathway; negative regulation of protein processing; glutathione metabolic process; neurogenesis; glutathione catabolic process
Cellular component: cytosol; trans-Golgi network; Golgi apparatus
Genetic constraint (gnomAD): Loss-of-function variants: 22 observed, 22.04 expected, observed/expected ratio (o/e) 1, 90% interval 0.71 to 1.42. The upper end of that interval is the gene's LOEUF score, 1.42, which puts it in group 5 of 6, group 1 being the genes least tolerant of losing a copy. Missense variants: 272 observed, 290.56 expected, observed/expected ratio (o/e) 0.94, 90% interval 0.85 to 1.03. Synonymous variants: 145 observed, 124.18 expected, observed/expected ratio (o/e) 1.17, 90% interval 1.02 to 1.34.
Homologues: Orthologues: chimpanzee CHAC1 (99% identical), macaque CHAC1 (99% identical), rabbit CHAC1 (95% identical), dog CHAC1 (93% identical), pig CHAC1 (92% identical), guinea pig CHAC1 (91% identical), rat Chac1 (89% identical), mouse Chac1 (88% identical), tropical clawed frog chac1 (53% identical), zebrafish chac1 (51% identical), Drosophila melanogaster CG10365 (44% identical), Caenorhabditis elegans F22F7.7 (34% identical). Paralogues in human: CHAC2 (41% identical).
Diseases named in the same sentence as CHAC1 in open-access papers:
CHAC1 is named in the same sentence as 104 diseases in open-access papers, as found by Europe PMC text mining. Sharing a sentence is not in itself a finding about the gene and the disease. The quoted sentences say what the papers report.
breast carcinoma (22 papers, 2012 to 2025). "High CHAC1 expression is associated with poor prognosis in breast cancer, ovarian cancer, renal hyaline carcinoma, and uveal melanoma." (PMID 39368995, 2024). "The upregulation of CHAC1 following PHGDH silencing has been implicated in breast cancer, and in AML; its overexpression is associated with high-risk prognosis and reduced overall survival." (PMID 38690164, 2024). "CHAC1’s expression also increases during ER and oxidative stress and is viewed as a risk prognostic factor for breast cancer and renal clear cell carcinoma." (PMID 38235126, 2023). "We have recently shown that high levels of CHAC1 are associated with increased proliferation, lymph node metastasis, and poor prognosis in breast cancer." (PMID 36568153, 2022). "Validating the association of CHAC1 and its transcript variants with survival within breast-cancer entities, a P-spline regression model confirmed the results of the main multivariate Cox model in sensitivity analysis." (PMID 22108517, 2012). "The mRNA expression values of total CHAC1 strongly correlated with the CHAC1 transcript variants 1 and 2 in breast cancer (r=0.94; P<0.001 and r=0.97; P<0.001)." (PMID 22108517, 2012). "Similarly, CHAC1 overexpression in breast cancer tissues is associated with lymph node metastasis and increased cell proliferation, indicating poor prognosis in breast cancer." (PMID 39335604, 2024). "Moreover, we found that a high mRNA expression of CHAC1 or related transcript variants were an independent poor prognostic marker for outcome in breast cancer patients." (PMID 22108517, 2012). "Therefore, high CHAC1 expression in breast cancer may be a vital indicator for diagnostic and prognostic analysis." (PMID 37313465, 2023). "Interestingly, ChaC1 was suggested as a novel biomarker because the overexpression of mammalian ChaC1 and its related transcript variants has been previously found to promote cell proliferation in breast cancer cell lines Hs578T and BT-20." (PMID 31878259, 2019). "In breast cancer, CHAC1 overexpression promotes both proliferation and migration, while in ovarian cancer, its impact is primarily restricted to cell migration, with minimal effect on proliferation." (PMID 41488051, 2025). "A study found that CHAC1 is a potential predictor of drug sensitivity and prognosis, as well as brain metastasis originating from primary breast cancer." (PMID 39335604, 2024). "On the other hand, transcription of the glutathione (GSH)-degrading enzyme chac glutathione specific gamma-glutamylcyclotransferase 1 (CHAC1) mediated by ATF4 enhances the ferroptosis of breast cancer cells induced by artesunate or cystine starvation." (PMID 38509409, 2024). "This proteotoxic stress, driven by the imbalance in thiol homeostasis, is a key mechanism through which CHAC1 mediates the paraptotic cell death pathway in breast cancer cells treated with auranofin and proteasome inhibitors." (PMID 39534397, 2024). "CHAC1 is upregulated in breast cancer and advanced clear cell renal cell carcinoma (ccRCC) and is associated with poor prognosis." (PMID 39368995, 2024). "Using multivariate Cox analysis, FBXO6, PMAIP1, ERP27, and CHAC1 were identified as independent prognostic factors in patients with breast cancer." (PMID 37313465, 2023). "We found a significantly reduced migration and proliferation in vitro, in CHAC1 knockdown Hs578T breast cancer cells and, conversely, we witnessed increased migration and proliferation in CHAC1-overexpressing cells." (PMID 22108517, 2012). "In the present study, the overall 5-year survival rate of breast cancer patients with low CHAC1 expression was 49% compared with only 35% for patients with high CHAC1 expression." (PMID 22108517, 2012). "Poorly differentiated tumours exhibited higher CHAC1 mRNA expression (breast cancer: P=0.004; ovarian cancer: P=0.024)." (PMID 22108517, 2012).
breast carcinoma (continued). "Additional studies will improve the understanding of the link between CHAC1 and patient resistance to breast cancer therapies." (PMID 22108517, 2012). "Knockdown of CHAC1 has also been shown to inhibit breast cancer proliferation and migration." (PMID 39834939, 2024). "Conversely, in some cancers, such as gastric cancer, breast cancer, and melanoma, CHAC1 has been correlated with poor prognosis, suggesting it may also play an oncogenic role." (PMID 39534397, 2024). "Similarly, the overall high CHAC1 expression in breast cancer samples significantly impacted patient prognosis and survival." (PMID 37313465, 2023). "CHAC1, a ferroptosis-related gene, is correlated with breast cancer." (PMID 36774490, 2023). "Moreover, it has been demonstrated that CHAC1 degrades GSH into 5-oxo-L-proline and cysteine-glycine dipeptide, which leads breast cancer cells to be highly susceptible to ER stress." (PMID 34679638, 2021). "Interestingly, ChaC1-overexpressing Hs578T breast cancer and HOC-7 ovarian carcinoma cell lines exhibited increased migration and proliferation." (PMID 31878259, 2019). "We found that CHAC1 is one of the largest changes in the gene expression induced by cystine starvation in the three TNBC cells, and that there is a significant positive correlation between ATF4 and CHAC1 gene expression in breast cancer patients and breast cancer cell lines." (PMID 29383104, 2017). "In BT-20 breast cancer cells, a 56% CHAC1 knockdown was revealed at the protein level." (PMID 22108517, 2012). "In previous studies, higher expression of CHAC1 could act as a protective role in accelerating apoptotic death of glioma through various pathways, and it was suggested to be included in prognostic prediction to aid the scheme of treatment in breast cancer." (PMID 34284774, 2021). "Comparative analysis with the well-established MCF-10A reference cell line revealed a significant upregulation of APOA5, CHAC1, EMID1, GOSR2, TCP1, and TMEM167A in breast cancer cell lines." (PMID 38300336, 2024). "Conversely, CHAC1’s role in ferroptosis makes it a potential biomarker and therapeutic target, with studies indicating that its modulation could be leveraged to induce ferroptosis selectively in breast cancer cells, thereby suppressing tumor proliferation and improving patient outcomes." (PMID 39534397, 2024). "However, in breast cancer, ATF4 upregulates the expression of ChaC glutathione specific gamma‐glutamylcyclotransferase 1 (CHAC1) to promote the cystine starvation‐induced ferroptosis." (PMID 37229485, 2023). "Taken together, the results of the present study show that like its paralog CHAC1, CHAC2 may also be an important biomarker and could have a potential therapeutic implication in breast cancer." (PMID 36568153, 2022). "Overexpression of ChaC1 increased the proliferation of breast cancer and ovarian cancer cell lines; however, it is not yet fully understood why the overexpression of the ChaC family proteins promotes the proliferation of certain cancer cell lines." (PMID 31878259, 2019). "Hence, we measured cell migration by means of an in vitro scratch assay and proliferation in Hs578T and BT-20 breast cancer and HOC-7 ovarian cancer wild-type cells, CHAC1 knockdown cells and cells treated with a scrbl siRNA as negative control." (PMID 22108517, 2012). "The roles of the DNAJB9, CHAC1, HERPUD1 genes in senescence induction have not been reported but these genes are all involved in tumorigenesis in breast cancers." (PMID 39466820, 2024).
ovarian carcinoma (14 papers, 2012 to 2025). A malignant neoplasm originating from the surface ovarian epithelium. "The expression of CHAC1 in breast and ovarian cancer cells and associated with significantly higher mortality in breast and ovarian cancer patients, implicating a possible role as a metastatic factor in these cancers." (PMID 38785562, 2024). "The mRNA expression values of total CHAC1 strongly correlated with the CHAC1 transcript variants 1 and 2 also in ovarian cancer (r=0.88; P<0.001 and r=0.96; P<0.001)." (PMID 22108517, 2012). "This is the first pilot study, which shows an association of CHAC1 mRNA expression in tumour tissues with the survival of breast and ovarian cancer patients." (PMID 22108517, 2012). "In ovarian cancer we observed only in younger patients (age <median age of 62.6 years as well as premenopausal women) an association between high CHAC1 mRNA expression levels and poor OS and RFS." (PMID 22108517, 2012). "Now, this work illustrates CHAC1 mRNA expression and associated clinical outcome in breast and ovarian cancer." (PMID 22108517, 2012). "Moreover, the expression level of Chac1 mRNA is increased in breast and ovarian cancers associated with poor prognosis, and knockdown of Chac1 results in decreased cell migration." (PMID 27302742, 2016). "High CHAC1 mRNA expression could be an independent indicator for elevated risk of cancer recurrence in breast and ovarian cancer." (PMID 22108517, 2012). "To analyse whether an aberrant CHAC1 mRNA expression is also associated with poor outcomes in other female malignancies, we analysed 103 ovarian cancer tissues and 30 normal ovarian specimens." (PMID 22108517, 2012). "Additionally, it has been identified that the overexpression of CHAC1 is associated with the poor outcomes of various cancers, including uveal melanoma, breast, and ovarian cancer, due to its substantial role in promoting tumour cell proliferation and migration." (PMID 35983595, 2022). "While its expression pattern varies across tumor types, CHAC1 is frequently upregulated in aggressive malignancies, such as breast and ovarian cancer, where it correlates with advanced tumor differentiation and potentially serves as a prognostic marker." (PMID 41488051, 2025). "For example, the downregulation of CHAC1 and PPP1R15A were associated with early mortality in ovarian cancer patients." (PMID 34253709, 2021). "Other studies in breast and ovarian cancer have shown that CHAC1 expression correlates with tumor differentiation and survival, suggesting that the observed ER stress in our models is likely stress-resolving and can promote disease progression." (PMID 33218188, 2020). "Depletion of intracellular glutathione by CHAC1 was initially considered pro-apoptotic but, in opposition to this, expression of CHAC1 in breast and ovarian cancers positively correlates with cancer grade and severity." (PMID 31100816, 2019). "In CHAC1-knockdown HOC-7 ovarian cancer cells we found a significantly reduced migration and conversely a tendency of an increased migration in CHAC1-overexpressing cells." (PMID 22108517, 2012). "Ovarian cancer patients aged younger than 62.6 years with high CHAC1 mRNA expression showed poorer relapse-free- and overall-survival (P=0.030 and P=0.012, respectively)." (PMID 22108517, 2012). "Subsequently, we conducted functional studies using short-interfering RNA-mediated knockdown and plasmid-mediated overexpression of CHAC1 in breast and ovarian cancer cells." (PMID 22108517, 2012). "Owing to the identified associations of CHAC1 mRNA expression and clinical outcome data in breast and in ovarian cancer patients, we were interested in functional effects of CHAC1 knockdown and CHAC1 overexpression in cancer cells." (PMID 22108517, 2012). "Univariate analysis of 103 ovarian cancer patients revealed prognostic significance for CHAC1 mRNA expression only in younger patients (<median age of 62.3 years) for OS (P=0.012) and RFS (P=0.03)." (PMID 22108517, 2012).
ovarian carcinoma (continued). "We identified a positive correlation between poor tumour differentiation and higher CHAC1 mRNA expression levels in breast and ovarian cancer." (PMID 22108517, 2012). "In summary, our data show that CHAC1 correlated with tumour differentiation and survival in breast and partly in ovarian cancer." (PMID 22108517, 2012). "In addition, CHAC1 and PPP1R15A downregulation was associated with shorter OS in ovarian cancer patients." (PMID 34253709, 2021). "CHAC1 overexpression in breast and ovarian cancer cells promotes proliferation and migration." (PMID 31100816, 2019). "Owing to the associations identified between high CHAC1 mRNA expression levels and poor survival, especially with RFS, in breast and partly in ovarian cancer patients, we hypothesised that CHAC1 may have a role in cell migration and proliferation." (PMID 22108517, 2012). "Chac1 mRNA levels were upregulated 2-5-fold in skeletal muscles of tumor-bearing mice in four cancer cachexia models characterized previously, including colon cancer C26, pancreatic cancer Pan02, ovarian cancer TOV21G, and fibrosarcoma HT-1080, when compared to nontumor bearing (NTB) mice." (PMID 37014882, 2023). "To elucidate the role of CHAC1 in ovarian cancer we analysed CHAC1 knockdown and overexpression in HOC-7 ovarian cancer cells." (PMID 22108517, 2012). "Hormone receptor-negative breast tumours and advanced-staged ovarian cancers demonstrated elevated CHAC1 mRNA expression levels (P<0.001 and P=0.026, respectively)." (PMID 22108517, 2012).
gastric cancer (12 papers, 2018 to 2025). A primary or metastatic malignant neoplasm involving the stomach. "The anti-proliferative effect of metformin in gastric cancer may be partly induced by the upregulation of CHAC1 caused via the silencing of lncRNA Loc100506691." (PMID 39368995, 2024). "Taken together with the results from our previous study in vitro, H. pylori‐induced CHAC1 overexpression in parietal cells may cause somatic mutations that further contribute to the development of gastric cancer." (PMID 31111570, 2019). "Oxidative DNA damage caused by H. pylori‐induced CHAC1 overexpression in infected gastric epithelial cells may directly contribute to the development of gastric cancer." (PMID 29632819, 2018). "On the other hand, CHAC1 plays a key role as a tumor suppressor gene in primary liver cancer, gastric cancer, prostate cancer, and oral squamous cell carcinoma." (PMID 40860820, 2025). "Critically, low CHAC1 expression confers resistance to ferroptosis in several cancers, including hepatocellular carcinoma, gastric cancer, prostate cancer, and oral squamous cell carcinoma." (PMID 40860820, 2025). "In this way, ALKBH5 directly downregulates CHAC1 and contributes to ferroptosis resistance in gastric cancer cells." (PMID 41488051, 2025). "In gastric cancer, the RNA demethylase ALKBH5 (Alkylated DNA repair protein alkB homolog 5) removes an m6A modification from CHAC1 mRNA, a mark normally associated with transcript stability." (PMID 41488051, 2025). "Evidence indicates that low CHAC1 expression serves as a key factor conferring chemoresistance across various malignancies, including hepatocellular carcinoma and gastric cancer." (PMID 40860820, 2025). "The RNA demethylase AlkB homolog 5 (ALKBH5), which is highly expressed in gastric cancer, can downregulate CHAC1 by removing m6A modifications." (PMID 40227215, 2025). "In contrast, CHAC1 functions as a tumor suppressor gene in primary liver cancer, gastric cancer, prostate cancer, and human oral squamous cell carcinoma." (PMID 39368995, 2024). "This upregulation of ChaC1 suggests that OP-B induces ferroptosis in gastric cancer cells, as ChaC1 is a marker of this form of cell death." (PMID 39534397, 2024). "Ophiopogonin B (OP-B) significantly influences ChaC1 in gastric cancer by increasing its mRNA levels." (PMID 39534397, 2024). "ChaC1 mRNA levels were markedly elevated in gastric cancer tissues treated with OP-B compared to adjacent normal tissues." (PMID 39534397, 2024). "In our study, we present additional evidence through the integration of RNA-seq and MeRIP-seq data, identifying CHAC1 as a potential downstream target of ALKBH5 in gastric cancer (GC)." (PMID 38007439, 2023). "Mechanistically, ALKBH5 downregulates CHAC1 expression by eliminating m6A modification, disrupting ROS homeostasis in gastric cancer." (PMID 38007439, 2023). "Fer-1, a lipid peroxidation inhibitor, significantly attenuated Tan IIA caused increased lipid peroxidation and Ptgs2, Chac1 expression, which indicated that Tan IIA indeed induced ferroptosis in BGC-823 and NCI-H87 gastric cancer cells." (PMID 32776119, 2020). "Thus, the pathway involving Loc100506691 and CHAC1 presents a potential target for therapeutic intervention in gastric cancer, leveraging metformin’s regulatory impact on this lncRNA." (PMID 39534397, 2024). "Consequently, CHAC1 serves as a key mediator in ferroptosis, aiding in the inhibition of gastric cancer progression." (PMID 39534397, 2024). "To ascertain whether CHAC1 plays a predominant role in ALKBH5-mediated gastric cancer proliferation, we generated two mouse models overexpressing these genes." (PMID 38007439, 2023). "In kidney renal and gastric cancer, CHAC1 could act as a biomarker to predict the long-term survival of patients." (PMID 38007439, 2023). "Moreover, CHAC1 modulates intracellular ROS levels, influencing the chemotherapy sensitivity of gastric cancer." (PMID 38007439, 2023).